SRRM1P2 (serine/arginine repetitive matrix 1 pseudogene 2)
Gene: Processed pseudogene on chromosome 3 (83,937,045 to 83,938,236, forward strand). Ensembl gene ENSG00000242195.
Diseases named in the same sentence as SRRM1P2 in open-access papers:
SRRM1P2 is named in the same sentence as 2 diseases in open-access papers, as found by Europe PMC text mining. Sharing a sentence is not in itself a finding about the gene and the disease. The quoted sentences say what the papers report.
Obesity (1 paper, 2023). Accumulation of substantial excess body fat. "The SNP rs6794880 (chr3:84,402,361) in SRRM1P2 was reported to be related to obesity, and we suspected that this locus might influence the development of obesity through regulating the DNAm at one CpG (chr3:84,330,462) in SRRM1P2 we identified." (PMID 36869404, 2023).
SRRM1P2 also shares sentences with these, for which no sentence is quoted: Hypertension (1 paper).